IL2 (interleukin 2)
Diseases named in the same sentence as IL2 in open-access papers (continued):
Sharing a sentence is not in itself a finding about the gene and the disease.
infection (continued). "The expression of inflammatory factor IL-2 in spleen decreased significantly from 1 to 3 weeks post infection (p < 0.01), and the expression of IL-2 was markedly higher than that in Nc group at 6 and 12 weeks post infection (p < 0.01)." (PMID 34421855, 2021). "FACS analysis of splenic T cells concerning the presence of CD69 showed that mice treated with anti-IL-2 mAb had increased numbers of CD4+CD69+ splenic T cells 21 days after initial infection." (PMID 34869064, 2021). "In the early stages of the infection, a group of cytokines and pro-inflammatory chemokines are expressed including interleukin-1β (IL-1β), IL-2, IL-6, interleukin-8 (IL-8), both IFN-α/β, tumor necrosis factor (TNFα), CCL, CCL3, CCL5, CCL2, and IP-10." (PMID 34220861, 2021). "Strikingly naive CD4 T cells from neonatal mice had a heightened capacity to phosphorylate STAT5 in response to IL-2, and antibody-mediated immunity can be boosted by removing IL-2 signaling during neonatal infection." (PMID 34665220, 2021). "Together, despite the more severe disease and enhanced utility of corticosteroids in patients receiving Ld-IL2, this therapy indeed decreased the incidence of infection." (PMID 34618873, 2021). "Infection with SARS-CoV-2 virus causes the body’s immune response in which pro-inflammatory cytokines such as TNF-α, IL-6, IL-1β, IL-2 and IFN-γ are secreted." (PMID 34575258, 2021). "On the contrary, a decreased percentage of IL-2+ CD8+ splenic T cells on day 21 after infection compared to days 0 or 4 was demonstrated." (PMID 34869064, 2021). "When comparison was made between different serotypes and primary/secondary infection, significant difference was observed in cytokines IL-1β, IL-2, IL-6, IL-8, IL-12, TNFα, IFNγ, GM-CSF, and IP-10." (PMID 34447698, 2021). "By contrast, IL-2+ T-cells at three months after vaccination were significantly higher than at any time point after infection." (PMID 34960185, 2021). "AE infection increases the expression of the IL-2 receptor and the consumption of IL-2, thereby inhibiting the immune activity of T lymphocytes and triggering the immune escape of parasites." (PMID 34256821, 2021). "As the proinflammatory cytokine, IFN-γ and IL-2 were released largely to limit T. gondii during different infection phases; they are considered to be indicator for triggering of CD4+ Th1 and CD8+ cytotoxic T cells." (PMID 35003067, 2021). "Flow cytometry analysis of mouse peripheral blood 4 d post-infection showed that TM cells derived from IL-2(Rapa+)/T-cells exhibited roughly a 2-fold greater expansion than TM cells derived from IL-2/T-cells." (PMID 35008461, 2021). "At day 8 post infection, all mice in the IL-2 treated group (n = 8) had already cleared the virus in lung tissues while only 50% of the surviving mice in the PBS treated group had done so, indicating enhanced anti-viral immunity." (PMID 34618873, 2021). "As shown in a range of studies, the simultaneous expression of the cytokines IFN-γ, TNF, and IL-2 enables T cells to a more effective immune response towards different infections in mice and men." (PMID 34351501, 2021). "The mRNA level of IL-1β, IL-8, TNF-α, and IL-2 was down-regulated (<1-fold) in the early stages of infection." (PMID 34603235, 2021). "Tumor necrosis factor alpha (TNF-α), IL-2, and granulocyte colony-stimulating factor (G-CSF) increased markedly following infection and remained relatively high throughout, with the exception of G-CSF, which dropped dramatically on 25 DPI." (PMID 33436428, 2021). "The rate of infection in the IL-2 group (7.3%, 16/219) was more than 3-fold lower than that of the non-IL-2 group (25.1%, 112/446) (P-value < 0.001)." (PMID 34618873, 2021). "Considering all this and in relation with the down-modulation of CD1d detected previously, both hRSV- and hMPV-infections seem to impair the production of IL-2 by iNKT cells in response to α-GalCer-loaded APC." (PMID 32463330, 2020).
infection (continued). "IL-2 is the growth factor for T cells, secreted by T cells and macrophages, participates in inflammatory regulation, regulates immunity, and increases infection resistance." (PMID 33505484, 2020). "We show here that sustained innate immune activation of IFN-γ during establishment of infection with S. Typhimurium in mice specifically reduces the ability of T cells to secrete IL-2 upon activation through the TCR." (PMID 32269573, 2020). "An independent study using LCMV‐infected mice showed that IL‐2 was required during the first 6 days of infection in order for CD8 memory T cells to mount an efficient response to the secondary infection." (PMID 32930455, 2020). "From these analyses, AIM2 rose as a lead PRR candidate for danger-signaling mediator during OAd.TNFa-IL2 infection." (PMID 32225009, 2020). "Both brain mRNA levels and cytokine concentrations of IL-4 and IL-10 were shown to be upregulated after infection with A. cantonensis, whereas those of IL-2 and IFN-γdecreased." (PMID 32635653, 2020). "On the other hand, CD4+CD44+IFN-γ+IL-17+IL-2+ T-cells (R = −0.7133, p < 0.0001) and CD4+CD44+IFN-γ+TNF-α+IL-2+ T-cells (R = −0.6845, p < 0.0001) showed correlation with bacterial load only post-infection." (PMID 32545304, 2020). "When compared with the levels of before infection, more IL-2+ CD4+ T cells and IL-2+ CD4+ TCM cells were elicited in the spleen and the lung of the CMFO/DMT group after infection with M. tuberculosis." (PMID 32953889, 2020). "Splenocytes obtained from mice on day 2 post infection produced IL-2, IFN-γ, and IL-17, levels of which were comparable with those produced by splenocytes from uninfected mice." (PMID 32269573, 2020). "Analysis of the cytokine subsets in the uGT showed that the Th1 effector cytokine subsets expressing TNFα/IFNγ and TNFα/IFNγ/IL-2 were present at day 14 and day 21 post infection." (PMID 31993218, 2020). "It was suggested that low levels of TNF-α, IL-2, IL-4, and IL-13 during early infection were predictive markers of chronic joint pain." (PMID 32471152, 2020). "The numbers of IFN-γ+TNF-α+IL-2+ T cells were the highest among the multifunctional T cells in the Rv2882c-Rv2005c immunized mice at 12 weeks post infection, and the numbers of IFN-γ+TNF-α+ T cells were sustained until 20 weeks postinfection." (PMID 32664238, 2020). "The existence of regulation between NK and CD8 T cells has been previously reported in many infection models and an antigen-independent IL-2 model." (PMID 32117218, 2020). "The study also reported that IL-2, IL-6, IL-18, and GM-CSF were significantly higher during the acute stages of B. rossi-infection." (PMID 32133380, 2020). "It was reported that infection of SARS-CoV-2 resulted in significant elevation of many cytokines such as IL-2, VEGF, PDGF and FGF." (PMID 33123542, 2020). "On the other hand, splenocytes isolated from mice after 5 days of infection with S.Typhimurium showed considerably reduced IL-2 secretion when compared with activated uninfected splenocytes." (PMID 32269573, 2020). "Our results show that infection of mice with S. Typhimurium renders T cells specifically incapable of producing IL-2." (PMID 32269573, 2020). "We show that infection of mice with Salmonella enterica serovar Typhimurium (S. Typhimurium) suppresses IL-2 and increases IFN-γ and IL-17 production from T cells activated in vivo or ex vivo through the T cell receptor." (PMID 32269573, 2020). "After infection, IL-2+ CD4+ T cells or TCM cells were still dominated in the lung of all vaccinated groups." (PMID 33117374, 2020). "The detection of 39% of the IL‐2 pDHSs in in vivo‐generated 2W1S‐specific Th1 memory T cells 56 days post‐infection indicates that these sites are epigenetically stable when the TCR signals are down‐regulated." (PMID 32930455, 2020). "Prolonged IL-2 signaling, especially in the context of inflammation, drives terminal effector differentiation, whereas curtailed IL-2 signaling during infection favors CD8 memory formation." (PMID 32991634, 2020).
infection (continued). "At 14 days post infection (directly after treatment) very high concentrations of IL-2, IL-13, IL-10, IFNγ, IL-6, and TNFα were observed." (PMID 32226027, 2020). "It was proven that during infection, secreted IL-2 and IL-6 play a potential role in apoptosis and T cell survival through increased transcription and translation of the FasL gene." (PMID 32349424, 2020). "For example, notch signaling (down‐regulated in infection animals in both species) regulates T‐cell differentiation together with other signaling pathways, such as IL2 and type I IFN (Amsen, Helbig, & Backer, 2015)." (PMID 32724523, 2020). "Infection with A. cantonensis has been confirmed to lower IL-2 and IFN-γ production in both humans and mice, which corroborates our results." (PMID 32635653, 2020). "The mRNA expression level of both IL-2 and IL-6 was notably increased after 1 and 2 h of infection and was further dramatically enhanced after 6 h of infection (p < 0.01)." (PMID 30736473, 2019). "We observed that huNSG mice that were infected with 105 infectious EBV particles also had significantly higher serum levels of IFNγ, TNFα, IL-10, and IL-2 compared to infection with 103 infectious EBV particles or PBS treated huNSG animals." (PMID 31145756, 2019). "For instance, in the RV144 trial, CD4+ T-cells secreting IL-2, TNF-α, IFN-γ, IL-4, and CD154 in response to HIV-1 envelope peptides were associated with lower infection rates in vaccine recipients." (PMID 31382453, 2019). "After Mtb infection, spleen lymphocytes from both BCG- and rBCG-DisA-immunized mice produced more cytokines of IFN-γ, IL-2, and IL-10 than infection control." (PMID 31333655, 2019). "Other tested cytokines were elevated or unchanged compared to controls during the respective infection phases, and only IL-2 exhibited downregulation during the early phase of infection." (PMID 31681308, 2019). "Our results imply that the improved protective efficacy of the Il2-/- memory CD4 T cells in the adoptive transfer model employed here is due largely to differences in the inflammatory response generated upon infection." (PMID 31412088, 2019). "In contrast, IL-2-producing CD44+CD4+ T cells were already detectable on day 3 but were most abundant on day 15 post-infection." (PMID 30677097, 2019). "Mice were sacrificed 7–10 days after the third immunization, the spleen and lymph gland cells were collected, and lymphocytes were prepared for T-cell IFN-γ and IL-2 cytokine secretion assays as these two immune factors are related to infection and disease." (PMID 30816178, 2019). "It has been reported that IL-2 plays an important role during primary infection in programming the development of memory CTLs to ensure full secondary expansion upon challenge." (PMID 31447845, 2019). "Other studies reported that Th1 cytokines (IFN-γ and IL-2) are detected in serum during infection and after subcutaneous and intramuscular immunization with diphtheria toxin, respectively." (PMID 31008105, 2019). "Although we observed similar impacts using TcR transgenic and polyclonal CD4 T cells, a comprehensive understanding of how and when IL-2 produced by CD4 T cell populations impacts infection requires further study." (PMID 31412088, 2019). "Dam 3 exhibited an increase above baseline in IL-2, IL-6, IL-7, and IL-15; notably, all cytokines increased on day 7 and returned to basal by day 14 post-infection." (PMID 30657788, 2019). "In the ELISA assays, IL-2 was significantly upregulated at the early stage (2 h) after infection (p < 0.05), and the peak IL-2 concentration (at 24 h) was notably greater than that observed in the control (p < 0.015)." (PMID 30736473, 2019). "It controls the signaling of a variety of cytokines, in particular interleukin-2, and seems to be critical for T cell proliferation and survival in response to infection." (PMID 31086608, 2019).
infection (continued). "We previously found that IAV-specific lung-resident memory CD4 T cells generated from naive TcR Tg donor cells displayed robust IL-2 production when assayed at day 30 post-infection and beyond." (PMID 31412088, 2019). "Curiously, at this later time-point, the only infection-induced phenotype observed for C57BL/6 animals was the significant increase in the IL-2 production by splenic CD4+ T cells." (PMID 30881923, 2019). "Infection was the factor responsible for the largest variation between cytokines and chemokines (significant in all except IL-2 and TGF-β)." (PMID 31681334, 2019). "On the contrary, CytoD induced a dose-dependent reduction of IL-2 production by DCs, IL-10 by PMNs and IL-1β by MPs in response to infection by all rBCG strains." (PMID 31921172, 2019). "In CD4+ T cells, the transcription factor Oct1/Pou2f1 is a dispensable transcription factor for T cell development and response to primary infection, but promotes expression of target genes, including Il2 and Ifng, under conditions of antigen reencounter." (PMID 31266507, 2019). "Among the tested proinflammatory and anti-inflammatory cytokines, there were significant differences in the mRNA expression levels of IL-2, IL-4, IL-6, and IL-10 following infection with the virulent vs. the attenuated strain (p < 0.05)." (PMID 31514454, 2019). "Two cell populations determine leishmanial condition: Th1 (IFN-γ, IL-2) in the protective condition and Th2 (IL-4, IL-10, and IL-13) in progressive infection." (PMID 30834079, 2019). "In the CD4+ T cell-depleted group, production of IL-2 and IL-10 were decreased in the early stage of infection, and production of IL-17 and TNF-α was decreased in both the early and late stages." (PMID 31608052, 2019). "Given that IL-2 is synthesized by activated T cells, it is perplexing that during infection, IL-2 levels were the same between the sexes even though male PBMCs were clearly proliferating." (PMID 31477151, 2019). "In agreement with the phenotypic changes induced in individual immune cells, H-1PV infection of PBMCs generates a TNF-α/IFN-γ/IL-2 signature that is accompanied by activation and focal proliferation of T cells, with the prevalence of CD4+ Th cells." (PMID 31060205, 2019). "Second, while ML29P50 and ML29 induced comparable T cell responses at day 7, at the late stage of the infection ML29P50 generated much stronger T cell immunity as assessed by IFN-ɣ/IL-2 ELISPOT in line with the strong immunomodulation potency of defective IPs." (PMID 30650607, 2019). "Deficiency of IL-10 improved the anti-virus ability of the mice at the early phase of infection through increasing either pro-inflammatory cytokines’ (IL-2, IL-6, IL-12, TNF-α, IFN-α, IFN-γ) production or PCV2-specific antibodies." (PMID 31551984, 2019). "The present study is the first to use WBA plus IL-2 quantification to determine the prevalence of asymptomatic infection." (PMID 31164191, 2019). "In particular, increased levels of IFN-γ establish a Th1-dominant microenvironment, inhibiting interleukin 2 (IL-2) activity, which plays an essential role in the priming of Th2 responses and protection against the infection." (PMID 31248010, 2019). "During infection, pathogen-derived H2S can inhibit lymphocyte proliferation by affecting the synthesis of interleukin-2 (IL-2)." (PMID 30573530, 2019). "We extended our analysis beyond the conventional IFNγ response by measuring TNFα, IL2, and IL17a producing T-cells as well, both in the periphery as well as at the site of the infection at various time points after infection." (PMID 31736945, 2019). "This suggests that the mechanism involves the regulation of TLR4 expression by IL-2, which then regulates the content of IgA in the urinary space, preventing the establishment of infection." (PMID 31911807, 2019).
infection (continued). "At 6 h post-infection, except GM-CSF and IL-2 were significantly higher in the ESRD group than in the control group, the levels of IL-8, IL-10, IL-12p40, TNF-α, MCP-1, and MIP-1b were found to be lower in the ESRD group." (PMID 31875015, 2019). "When CD8+ T cells were depleted, the amount of IL-10 produced 7 days after infection and the amount of IL-2 produced 17 days after infection significantly increased relative to the infected control group." (PMID 31608052, 2019). "Protection from infection was increased from ~80% in the chIL-2 or chIL-7 vector alone groups to 93% seen in the IL-2/IL-7 bicistronic vector group." (PMID 31137731, 2019). "In our series, apart from high levels of GM-CSF and IL-2 that were observed at 6 h post-infection, impaired production of immune mediators was observed at a later stage post-infection in the ESRD group." (PMID 31875015, 2019). "Dam 2 had an increase in IL-1β, IL-2, IL-6, IL-7, IL-12, IL-15, IL-16 and IL-17A, peaking on day 14 post-infection for all but IL-12 and IL-15 which peaked on day 7 post-infection." (PMID 30657788, 2019). "In the panel of cytokines that differentiates between infection and rejection, IL-2 exhibited the highest fold increase." (PMID 30696462, 2019). "The concentration of IL-6 was significantly increased by 12 dpi, peaked at 20 dpi and decreased afterwards whereas the concentrations of IL-1β and IL-2 remained unchanged along the infection." (PMID 30455700, 2018). "Primary CD4+ T cells were activated with αCD3/CD28 beads + 20 U/mL IL-2 for 3 days before infection with different amounts of HIVGKO (input, ng/p24) and analyzed by flow cytometry 4 days post-infection." (PMID 29714165, 2018). "Briefly, CD4+ T-cells were purified from blood of four healthy donors and activated for 72 hr with αCD3/CD28 beads and 20 U/ml IL-2 before infection with HIVGKO." (PMID 29714165, 2018). "Direct correlations were observed between CD4+ T cell activation and the percentages of IL-2-producing or ki67-expressing CD4+ T cells in patients at the acute phase of infection." (PMID 29636753, 2018). "By contrast, IL-2 levels following exposure to DCs harvested 72 h after infection were barely detectable." (PMID 29940854, 2018). "After infection by oncolytic virus, cancer cell upregulates the production of reactive oxygen species and some cytokines (e.g. interleukin-2 and interferon-γ) to counteract the infection." (PMID 30473928, 2018). "Infection clearly induced a dimorphic pattern; it reduced IL-2 mRNA expression in intact females compared to that in intact males while decreasing IL-2 mRNA expression in sham-infected males compared to that in sham-infected females (P < 0.05)." (PMID 30515051, 2018). "The LJM17-immunized dogs presented a prolonged pattern of pro-inflammatory response that persisted until 4 months after infection, with the exception of IL-2, CXCL10, IL-8, and CCL2." (PMID 30519235, 2018). "Another important difference between infection and skin immunization was the production of high levels of IL-2 by skin immunization with iC+CT, compared to the infection with LC." (PMID 29946313, 2018). "TCM cells are a population with the capacity to produce high levels of IL-2, and this population was generated by skin immunization with iC+CT, while the infection mainly generated CD4+ T cells with an effector phenotype." (PMID 29946313, 2018). "In conclusion, FAdV-4 (SDSX) induces the upregulation of antibody titers, IL-2, and IFN-γ expression in 25-day-old meat ducks at the early infection stage and causes damage to the tissues of many immune organs, especially the liver and kidney." (PMID 30510548, 2018). "In our study, we only found significant difference of TNF-α response in the 2000 CFU level of infection between the two strains, same as other cytokines including IL-4, IL-10, GM-CSF, IL-1β, IL-2, IL-6, IL-13, and IL-18." (PMID 30577452, 2018).